P2RY1 (purinergic receptor P2Y1)
Description:
Receptor for extracellular adenine nucleotides such as ADP. In platelets, binding to ADP leads to mobilization of intracellular calcium ions via activation of phospholipase C, a change in platelet shape, and ultimately platelet aggregation.
Synonyms: P2Y1; SARCC
Tractability: Small molecule: a drug acting on it is in phase 2 or 3 trials; a structure with a bound ligand is known; a high-quality ligand is known; it belongs to a druggable protein family. Antibody: UniProt places it where antibodies can reach, with high confidence; its Gene Ontology location is reachable by antibodies, with high confidence; UniProt predicts a signal peptide or a membrane-spanning region. PROTAC: a small molecule that binds it is known.
Target class: Purine receptor; Small molecule receptor (family A GPCR); Membrane receptor; Family A G protein-coupled receptor; Nucleotide-like receptor (family A GPCR)
Chemical probes: BPTU (high quality), CHEMBL2333767, PD082073, PD084704, PD084762
Gene: Protein-coding gene on chromosome 3 (152,835,131 to 152,841,439, forward strand). Ensembl gene ENSG00000169860.
Subcellular location: Cell membrane
Pathways (Reactome):
Signal Transduction: G alpha (q) signalling events; P2Y receptors
Hemostasis: ADP signalling through P2Y purinoceptor 1
Gene Ontology:
Molecular function: ATP binding; G protein-coupled ADP receptor activity; protein binding; A1 adenosine receptor binding; G protein-coupled ATP receptor activity; G protein-coupled purinergic nucleotide receptor activity; scaffold protein binding; signaling receptor activity; signaling receptor regulator activity; ADP binding; G protein-coupled receptor activity; protein heterodimerization activity
Biological process: cellular response to purine-containing compound; phospholipase C-activating G protein-coupled receptor signaling pathway; regulation of cell shape; adenylate cyclase-inhibiting G protein-coupled receptor signaling pathway; cell surface receptor signaling pathway; cellular response to ATP; G protein-coupled purinergic nucleotide receptor signaling pathway; G protein-coupled receptor signaling pathway; positive regulation of cytosolic calcium ion concentration; positive regulation of ERK1 and ERK2 cascade; protein localization to plasma membrane; signal transduction involved in regulation of gene expression; blood vessel diameter maintenance; eating behavior; G protein-coupled adenosine receptor signaling pathway; glial cell migration; negative regulation of norepinephrine secretion; platelet activation; positive regulation of hormone secretion; positive regulation of inositol trisphosphate biosynthetic process; positive regulation of penile erection; positive regulation of transcription by RNA polymerase II; regulation of presynaptic cytosolic calcium ion concentration; regulation of synaptic vesicle exocytosis; relaxation of muscle; and 2 more
Cellular component: cell surface; cilium; plasma membrane; cell body; dendrite; postsynaptic density; postsynaptic membrane; apical plasma membrane; basolateral plasma membrane; glutamatergic synapse; membrane; presynaptic active zone membrane
Genetic constraint (gnomAD): Loss-of-function variants: 14 observed, 23.47 expected, observed/expected ratio (o/e) 0.6, 90% interval 0.39 to 0.93. The upper end of that interval is the gene's LOEUF score, 0.93, which puts it in group 3 of 6, group 1 being the genes least tolerant of losing a copy. Missense variants: 395 observed, 498.34 expected, observed/expected ratio (o/e) 0.79, 90% interval 0.73 to 0.86. Synonymous variants: 200 observed, 209.22 expected, observed/expected ratio (o/e) 0.96, 90% interval 0.85 to 1.08.
Homologues: Orthologues: chimpanzee P2RY1 (99% identical), macaque P2RY1 (99% identical), rabbit P2RY1 (97% identical), pig P2RY1 (96% identical), rat P2ry1 (95% identical), mouse P2ry1 (95% identical), guinea pig P2RY1 (95% identical), dog P2RY1 (87% identical), tropical clawed frog p2ry1 (81% identical), zebrafish p2ry1 (69% identical). Paralogues in human: P2RY4 (35% identical), P2RY2 (32% identical), OXGR1 (30% identical), P2RY6 (30% identical), SUCNR1 (29% identical), HCAR3 (24% identical), HCAR2 (23% identical), HCAR1 (21% identical), GPR31 (21% identical), GPR42 (20% identical), FFAR3 (20% identical), OXER1 (20% identical), and 3 more.
Diseases named in the same sentence as P2RY1 in open-access papers:
P2RY1 is named in the same sentence as 127 diseases in open-access papers, as found by Europe PMC text mining. Sharing a sentence is not in itself a finding about the gene and the disease. The quoted sentences say what the papers report.
Stroke (10 papers, 2014 to 2025). Sudden impairment of blood flow to a part of the brain due to occlusion or rupture of an artery to the brain. "The reverse situation (more loss-of-function mutations in the IS group), as observed in this study, indicates that other mechanisms could be responsible for pro-stroke activity associated with P2RY1/P2RY12 receptors." (PMID 29232918, 2017). "A recent RNAseq study of the TA muscle using a mouse stroke model in 5 m mice found altered transcriptomes compared to age-matched non-stroke mice including: an upregulation in stroke mice >log2fc1 of Gadd45a, Shroom3, Chrna2, and MuSK, along with downregulation (log2fc < −1) of P2ry1." (PMID 37876943, 2023).
atherosclerosis (9 papers, 2015 to 2025). A disease characterized by the build-up of fatty material and calcium deposition in the arterial wall resulting in partial or complete occlusion of the arterial lumen. "PIK3CD and P2RY1 have not been reported in MI and atherosclerosis; however, Pik3cd is a critical gene in adipose-derived stem cells, which is the response to inflammation, which may be referred to in studies on diabetes." (PMID 34925642, 2021).
type 2 diabetes (7 papers, 2016 to 2023). "This notion is further supported by the presence of type 2 diabetes susceptibility signals intersecting eQTLs for the ADRA2A, CHRNB4 and P2RY1 genes." (PMID 36897571, 2023). "PAK3, CD44, CD5, SOCS3, VAV1, and PIK3CD are negatively correlated with cardiac systolic function, and P2RY1 is positively correlated with LVEF, which may be referred to in studies on type 2 diabetes." (PMID 34925642, 2021).
asthma (5 papers, 2016 to 2025). "According to the differential analysis of microarray GSE64913, P2Y1 was found to be differentially expressed in asthma, and P2Y1 is also listed as P2RY1 in National Center for Biotechnology Information (NCBI)." (PMID 34291079, 2021). "It would be intriguing to explore how P2RY1 contributes to alleviating the symptom of asthma and COPD." (PMID 33390983, 2020). "Notably, P2RX1, P2RX4, P2RX7, P2RY1, P2RY11, and P2RY14 were revealed as the most highly expressed purinergic receptors in lung tissue, therefore suggesting that these receptors have good potential as therapeutic targets for asthma and other respiratory diseases." (PMID 35386996, 2021).
prostate carcinoma (4 papers, 2011 to 2022). A carcinoma that arises from epithelial cells of the prostate gland. "Although there have been no reports of P2RY1 and CALCRL involved in lung diseases and cancer, they all have been demonstrated to play important roles in other cancers, such as bladder cancer, prostate cancer, and acute myeloid leukemia." (PMID 34039311, 2021).
status epilepticus (4 papers, 2018 to 2024). Status epilepticus is defined as a continuous seizure lasting more than 30 min, or two or more seizures without full recovery of consciousness between any of them. "During status epilepticus, neurons, astrocytes, and microglia release ATP, activating the purinergic receptor P2Y1 on astrocytes and further exacerbating neuronal excitotoxicity." (PMID 39876842, 2024). "Analysis of the hippocampus 14 days-post status epilepticus revealed increased P2ry1, P2ry2, and P2ry6 transcription and increased P2Y1, P2Y2, and P2Y12 protein levels." (PMID 29563872, 2018). "Status epilepticus: Increased P2ry2, P2ry4, and P2ry6 and decreased P2ry1, P2ry12, P2ry13, and P2ry14 transcript levels; increased P2Y1, P2Y2, P2Y4, and P2Y6 and decreased P2Y12 protein levels." (PMID 29563872, 2018).
thrombotic disease (4 papers, 2019 to 2024). The formation of a blood clot in the lumen of a vessel or heart chamber; causes include coagulation disorders and vascular endothelial injury. "Our finding that CYP2C19 expression is reduced with WAA while P2RY1 expression is inversely increased suggests that clopidogrel resistance and susceptibility of AAs to thrombotic disease may be due to ancestry-associated gene expression as an underlying mechanism." (PMID 31798965, 2019).
lung carcinoma (3 papers, 2019 to 2022). "The orthologues were related to DHDH, ATP8B3, and P2RY1 genes, expressed in the lipid membrane, and directly related to skin and lung cancer genes (APP and APPBP2), suggesting that they may share mechanisms among these diseases." (PMID 36542226, 2022). "Next, we determined the expression levels of P2X sub-families P2RX1–7 and P2Y receptors P2RY1, P2RY2, P2RY4, P2RY5 (LPAR6), P2RY6, P2RY7 (LTB4R), P2RY8, P2RY9 (LPAR4), P2RY10–14 in normal lung tissues and lung cancer tissues." (PMID 32638267, 2020).
melanoma (3 papers, 2017 to 2025). A malignant, usually aggressive tumor composed of atypical, neoplastic melanocytes. "In this study, we also showed the beneficial effects of the P2RY1 agonist, which has been shown in other cancer models, such as melanoma, where the P2RY1 receptor is highly expressed." (PMID 36879646, 2023).
Von Willebrand disease (3 papers, 2014 to 2021). von Willebrand disease (VWD) is a hereditary bleeding disorder caused by a genetic anomaly leading to quantitative, structural or functional abnormalities of the Willebrand factor (von Willebrand factor; VWF). "Platelet G protein-coupled receptor genes P2RY1, F2R, F2RL3, TBXA2R and PTGIR were sequenced in 146 index cases with type 1 von Willebrand disease and the potential effects of identified single nucleotide variations were assessed using in silico methods and heterologous expression analysis." (PMID 26630678, 2015).
acute myeloid leukemia (2 papers, 2021). Acute myeloid leukemia (AML) is a group of neoplasms arising from precursor cells committed to the myeloid cell-line differentiation. "Comparing with other cancer types, glioblastoma multiforme and acute myeloid leukemia showed a significant upregulation of P2RY1 and P2RY2, respectively, compared to their normal tissues, and conversely, the low expression of the genes provided more advantage in the overall patient survival." (PMID 34833046, 2021).
cognitive decline (2 papers, 2013 to 2023). "In addition, excessive amounts of ATP released by HCs activated purinergic receptor P2Y1, which was also related to cognitive decline." (PMID 38110991, 2023).
gastric cancer (2 papers, 2023 to 2024). A primary or metastatic malignant neoplasm involving the stomach. "Immunohistochemical staining data obtained from the HPA database demonstrated the downregulated expression of proteins encoded by P2RY1 in stomach cancer tissue." (PMID 36879646, 2023). "Also, immunohistochemical staining data obtained from the HPA database demonstrated the downregulated expression of proteins encoded by P2RY1 in stomach cancer tissue." (PMID 36879646, 2023). "We then used the transwell system to investigate the effect of P2RY1 on gastric cancer cell migration." (PMID 36879646, 2023). "The expression of P2RY1 differed markedly among the two sample types with diffuse gastric cancer tissues showing significantly lower level protein expression of P2RY1 compared with intestinal gastric cancer tissues." (PMID 36879646, 2023). "Our results have shown that four higher methylated sites of P2RY1’s promoter region can be used as markers for the prognosis of gastric cancers." (PMID 36879646, 2023). "Among the genes analyzed, P2RY1 had four high methylated sites within its promoter region, whereas its mRNA level was low in gastric cancer tissues." (PMID 36879646, 2023). "Moreover, we analyzed the expression levels of P2RY1 in various gastric cancer cell lines by Western blotting to determine how P2RY1 affected the development of gastric cancer." (PMID 36879646, 2023). "We showed that the selective activation of P2RY1 via its agonist, MRS2365, can induce ERK1/2 phosphorylation and subsequent ELK1/c-Fos/c-Jun phosphorylation, suggesting the crucial role of ERK1/2 signaling in gastric cancer cells." (PMID 36879646, 2023). "In summary, we have demonstrated that gastric cancer tissues have highly methylated P2RY1 gene and relatively low expression level of P2RY1 mRNA compared with noncancerous tissues." (PMID 36879646, 2023). "Studies showed that the levels of P2RY1 mRNA in aggressive gastric cancer tissues are low compared with those in noncancerous gastric tissues." (PMID 36879646, 2023).
amyloidosis (1 paper, 2023). A disorder characterized by the localized or diffuse accumulation of amyloid protein in various anatomic sites. "The link between the activity and or expression of CD39 and P2RY1, and how they are modified upon miR-155 deletion in amyloidosis mice, should be investigated further." (PMID 36879321, 2023).
aspiration pneumonia (1 paper, 2020). "Hence, increasing P2RY1 functional studies will help to shed lights on promoting the development of pharmaceutical drugs against swallowing disorders related diseases such as dysphagia and aspiration pneumonia in the clinic." (PMID 33390983, 2020).
Depression (1 paper, 2013). "Both the QIDS and HRSD displayed positive associations for depression and gene expression for ion channels P2RX1 and P2RY1, further strengthening the possible relationship of ion channels and depression." (PMID 24143878, 2013). "With the DD sample, greater depression severity (whether defined by QIDS or by HRSD scores) was associated with higher expression of ion channels P2RX1 and P2RY1." (PMID 24143878, 2013). "Finally, two additional ion channel genes, P2RX1 and TRPV4, as well as two of the genes from our primary analysis, IL-10 and P2RY1, were related to depression severity as assessed by the QIDS and/or HRSD." (PMID 24143878, 2013). "Depression severity was related to increased IL-10, P2RY1, P2RX1, and TRPV4 expression." (PMID 24143878, 2013). "Of the 9 ion channel receptors that we examined, P2RX7, TRPV1, and P2RY1 were upregulated in female patients during a depressive episode, and P2RY1 expression was positively related to depression severity along with 2 other ion channel receptors, TRPV4 and P2RX1." (PMID 24143878, 2013). "Our findings also provided initial evidence of possible dysregulation in 3 relatively novel targets for depression: ion channels TRPV1, P2RX7 and P2RY1." (PMID 24143878, 2013).
lung adenocarcinoma (1 paper, 2021). A carcinoma that arises from the lung and is characterized by the presence of malignant glandular epithelial cells. "Our bioinformatic analysis identified six downregulated DEGs (EDNRB, RXFP1, P2RY1, CALCRL, TEK, and ANGPT1) between lung adenocarcinoma and normal lung tissues based on two different microarray datasets." (PMID 34039311, 2021).
non-melanoma skin carcinoma (1 paper, 2021). "Furthermore, the P2Y purinergic receptor 1 (P2RY1), which has been shown to serve as an unfavorable prognostic marker in renal and non-melanoma skin cancers (, (Human Protein Atlas)), is also predicted to promote LUAD tumor progression at the stage 2–3 interface." (PMID 34940617, 2021).
Pancreatic cancer (1 paper, 2021). "Pancreatic cancer cells express the purinergic receptor P2Y12, that is an ADP receptor found mainly on platelets." (PMID 34858977, 2021).
cancer (22 papers, 2014 to 2025). A tumor composed of atypical neoplastic, often pleomorphic cells that invade other tissues. "Recently, P2RY1, a member of GPCRs, has emerged as a cancer target because of its critical role in tumor growth and metastasis." (PMID 36879646, 2023). "Moreover, five genes, including CITED2, C8orf44‐SGK3, FUZ, P2RY1, and SIX2, were associated with carcinoma migration." (PMID 38363001, 2024). "The high expression of P2RY1 and P2RY2 conferred better overall survival benefit to the patients as the cancers resembled more ‘normal tissue’ receptor expression." (PMID 34833046, 2021).
tumor (17 papers, 2013 to 2026). "Studies from our group and others have demonstrated that tumor cells upregulate the P2 purinergic receptors P2RY1, P2RY2, P2RX3 and P2RX7 and utilize extracellular ATP to support tumor growth and metastasis." (PMID 33420030, 2021).
infection (7 papers, 2021 to 2025). The state of being infected such as from the introduction of a foreign agent such as serum, vaccine, antigenic substance or organism. "Further, by reducing P2Y1 receptor signaling with the antagonist BPTU or by CRISPR-Cas9-mediated knockdown of P2RY1 prevented the formation of ICWs but did not prevent infection." (PMID 33604766, 2021).
neurological disease (1 paper, 2024). "We analyzed publicly available datasets whether P2ry1/P2RY1 and Igfbp2/IGFBP2 transcripts are upregulated in other neurological disease models." (PMID 39117630, 2024).
P2RY1 also shares sentences with these, for which no sentence is quoted: acute coronary syndrome (7 papers); diabetes (7); acute myocardial infarction (6); renal cell carcinoma (6); astrocytoma (5); ischemia (5); breast carcinoma (4); epilepsy (4); ischemic stroke (4); Sepsis (4); Thrombocytopenia (4); Bernard-Soulier syndrome (3); Cerebral ischemia (3); COVID-19 (3); Glanzmann thrombasthenia (3); Obesity (3); ovarian carcinoma (3); ST Elevation Myocardial Infarction (3); Alzheimer disease (2); cardiovascular disease (2); cerebral aneurysms (2); colitis (2); colorectal cancer (2); glioma (2); Hypertension (2); inflammatory bowel disease (2); malaria (2); myocardial ischemia (2); neuroblastoma (2); osteosarcoma (2).
A further 74 diseases each share a sentence with P2RY1 in 2 papers or fewer.